PTH (parathyroid hormone)
Diseases named in the same sentence as PTH in open-access papers (continued):
Sharing a sentence is not in itself a finding about the gene and the disease.
breast tumor (2 papers, 2018 to 2023). "Taken together, our data show that administration of PTH prior to tumour cell injection significantly increased the number of skeletal breast tumours compared to control, mainly in sites outside the hind limbs." (PMID 30261597, 2018).
calcium kidney stones (2 papers, 2019 to 2024). "All patients with recurrent calcium kidney stones should be advised to take 1000 to 1200mg of Ca per day through diet according to EAU guidelines, thus the significant change of PTH may be due in part to patient's sufficient Ca intake." (PMID 30735332, 2019).
cardiac arrest (2 papers, 2021 to 2023). Cessation of breathing and/or cardiac function. "One participant in the TransCon PTH group suffered a sudden fatal cardiac arrest deemed unrelated to study treatment." (PMID 36271471, 2023).
carotid atherosclerosis (2 papers, 2014 to 2017). A thickening and loss of elasticity of the walls of carotid arteries that occur with formation of atherosclerotic plaques. "Only a small number of studies have examined the independent association between both serum vitamin D and PTH with carotid atherosclerosis or arterial stiffness in large community-based populations." (PMID 29088221, 2017). "To date, although some epidemiological studies have reported an association between serum vitamin D or PTH with carotid atherosclerosis or arterial stiffness, the associations are inconsistent." (PMID 29088221, 2017). "Although previous studies reported an association between serum vitamin D and parathyroid hormone (PTH) with carotid atherosclerosis or arterial stiffness, these were inconsistent." (PMID 29088221, 2017). "In conclusion, we demonstrated that 25(OH)D has a negatively correlation with carotid atherosclerosis even after adjusting for conventional CVD risk factors, PTH, liver and renal function in postmenopausal women with normal blood glucose levels and normal blood pressure." (PMID 25528383, 2014). "We were unable to explain the relationship between vitamin D, PTH, and CVD using structural vascular markers of carotid atherosclerosis such as IMT and plaques." (PMID 29088221, 2017). "Therefore, we could hypothesize that serum vitamin D and PTH might affect CVD via pathways not involving carotid atherosclerosis, such as IMT or plaques." (PMID 29088221, 2017).
chondrosarcoma (2 papers, 2014 to 2016). A malignant cartilaginous matrix-producing mesenchymal neoplasm arising from the bone and soft tissue. "A high level of PTHrP expression was found in human chondrosarcoma tissues, and recombinant PTH exhibited positive promotion in tumor cell proliferation and invasion." (PMID 25365173, 2014).
chronic hepatitis B (2 papers, 2005 to 2018). "In conclusion, our study suggest that BMD of femur, serum IL-2r, IL-6, IL-8, PTH, and CTX levels were higher in children with chronic hepatitis B treated with IFN-alpha alone or combination with lamivudine than in healthy children." (PMID 16171525, 2005). "In our study, while serum PTH and CTX levels were higher in children with chronic hepatitis B than in healthy controls, there was no significant different in respect to serum osteocalcin and ALP levels." (PMID 16171525, 2005). "While serum IL-2r (p = 0.002), IL-6 (p = 0.001), IL-8 (p = 0.013), PTH (p = 0.029), and CTX (p = 0.021) levels were higher in children with chronic hepatitis B than in healthy controls, there was no significant different in respect to serum IL-1β, TNF-α and osteocalcin levels." (PMID 16171525, 2005).
congenital heart defect (2 papers, 2016 to 2021). "Recently, several studies also demonstrated this gene was related to multiple human diseases, such as duodenal adenocarcinoma, congenital heart disease, meningiomas, and circulating parathyroid hormone formation." (PMID 34351079, 2021). "Recent studies have demonstrated that RSPH14 is associated with human diseases, such as in rhabdoid tumors, duodenal adenocarcinoma, congenital heart disease, meningiomas, and circulating parathyroid hormone formation." (PMID 34351079, 2021).
degenerative disc diseases (2 papers, 2018 to 2022). "As an important hormone that regulates the balance of calcium and phosphorus, parathyroid hormone (PTH) has also been found to have an important function in intervertebral disc degeneration (IVDD)." (PMID 35265269, 2022). "Therefore, we speculated that PTH could maintain the homeostasis of intervertebral discs and could have great potential for the treatment of degenerative disc diseases." (PMID 35265269, 2022).
dilated cardiomyopathy (2 papers, 2019 to 2025). Cardiomyopathy which is characterized by dilation and contractile dysfunction of the left and right ventricles. "The target genes of Other-1_19 is predominantly associated with parathyroid hormone synthesis, secretion and action, dilated cardiomyopathy and circadian entrainment." (PMID 41415269, 2025).
enamel hypoplasia (2 papers, 2022 to 2024). "In this study, enamel hypoplasia, MIH/HSPM, and non-MIH/HSPM demarcated opacities were grouped as the main phenotype “DDE” once the hypothesis raised here is that the candidate genes VDR and PTH are involved in DDE regardless of the subphenotype." (PMID 38922252, 2024).
Erosive gastritis (2 papers, 2018 to 2019). "Erosive gastritis and peptic ulcer are the most common upper gastrointestinal disorders and maybe the factors such as an increase in gastrin and stomach acid, increased parathyroid hormone, decreased mucosal resistance and delayed gastric emptying are the main causes." (PMID 29564060, 2018).
fatty liver disease (2 papers, 2022). A reversible condition wherein large vacuoles of triglyceride fat accumulate in liver cells via the process of steatosis. "However, whether PTH has a pervasive effect on non-alcoholic liver steatosis and the underlying mechanisms for PTH regulating hepatic lipid metabolism is not clear." (PMID 36060945, 2022). "Our findings showed that intermittent administration of PTH reduced body weight gain and fat mass, and alleviated hepatic steatosis in both DIO mice and mid-life db/db mice." (PMID 36060945, 2022). "Here, we report that intermittent administration of PTH ameliorated non-alcoholic liver steatosis in diet-induced obese (DIO) mice and db/db mice, as well as fasting-induced hepatic steatosis." (PMID 36060945, 2022). "Given the involvement of PTH in adipocyte lipolysis, we thought to determine whether the lipolytic action could lead to hepatic steatosis under NCD feeding." (PMID 36060945, 2022). "In the current study, we explored the novel therapeutic effects of PTH on liver steatosis." (PMID 36060945, 2022). "Notably, excess PTH level was correlated with increased serum free fatty acid due to lipolytic action of adipose tissue, which may flux into the liver contributing to hepatic steatosis." (PMID 36060945, 2022).
fibroma (2 papers, 2014 to 2025). A non-metastasizing neoplasm arising from the fibrous tissue. "It is characterized by increased values of PTH, ossifying fibromas of the jaws, and in some cases neoplasms of the kidneys/or the uterus." (PMID 40115416, 2025).
gastrinoma (2 papers, 2018 to 2020). "Parathyroid surgery not only grants the restoration of normal serum parathyroid hormone (PTH) and calcium level, but is also beneficial for the control of gastrin oversecretion in MEN1 patients with a concomitant active gastrinoma." (PMID 30319541, 2018). "Regarding the association of GEP–NET and HPT, patients presenting with both gastrinoma and HPT have been reported to have a tendency for higher PTH levels and a higher percentage of urolithiasis than in patients without gastrinoma." (PMID 32276412, 2020).
giant cell tumors of bone (2 papers, 2013 to 2025). "It is well known that brown tumors, or osteoclastomas, are caused by localized, rapid, osteoclastic removal of bone secondary to the direct effects of PTH on the bone; it is actually a giant cell lesion and often appears as an expansile osteolytic lesion of the bone." (PMID 24024056, 2013). "Moreover, estimation of serum calcium and PTH levels is necessary since the radiologic and pathologic makeup of PHPT, giant cell tumors of bone, and central giant cell granulomas resemble each other." (PMID 39958142, 2025).
Gitelman syndrome (2 papers, 2018 to 2022). Gitelman syndrome (GS), also referred to as familial hypokalemia-hypomagnesemia, is characterized by hypokalemic metabolic alkalosis in combination with significant hypomagnesemia and low urinary calcium excretion. "Accordingly, decreased PTH secretion and decreased responsiveness of PTH to ionized calcium have been suggested in small cohorts of patients with Gitelman syndrome." (PMID 35137195, 2022). "In recent years, several investigators have observed abnormal levels of parathyroid hormone (PTH) and serum phosphate in patients with Bartter and Gitelman syndrome." (PMID 35137195, 2022).
Glomerular sclerosis (2 papers, 2020 to 2025). Accumulation of scar tissue within the glomerulus. "The mechanisms are dependent not only on the regulation of calcium, phosphorus, and parathyroid hormone (PTH) levels in the blood but also on the reduction of glomerular sclerosis and interstitial fibrosis by 1,25(OH)2D3." (PMID 32766307, 2020).
haemophilia (2 papers, 2020 to 2025). "The study highlights a high rate of low BMD and 25-OH-D3 deficiency in hemophilia patients, with the PTH/Ca ratio shown to be useful in predicting BMD." (PMID 40075885, 2025). "For the first time in evaluating bone metabolism in patients with hemophilia, we applied the PTH/Ca ratio, which was significantly higher in patients with low BMD." (PMID 40075885, 2025). "The PTH/Ca ratio is suggested as an accessible, cost-effective, and practical test for evaluating BMD in hemophilia patients." (PMID 40075885, 2025).
homocysteinemia (2 papers, 2021 to 2022). "Lastly, malabsorption of vitamin D, vitamin K, and calcium will increase the incidence of bone demineralization through different mechanisms such as increased PTH, homocysteinemia, and activation of the ROS pathway." (PMID 35103143, 2021).
hydronephrosis (2 papers, 2022). Collection of urine in the renal pelvis that results in dilatation of the renal pelvis and calyces. "Low PTH levels reduce calcium tubular reabsorption, and during pregnancy are associated with urinary stasis secondary to hydronephrosis." (PMID 35627905, 2022).
hyperostosis (2 papers, 2021 to 2023). Excessive thickening of bone. "We hypothesize that this may be secondary to her longstanding wide fluctuations in PTH levels due to non-compliance with her calcitriol, thereby causing hyperostosis, similar to the mechanism by which parathyroid hormone analogs induce bone formation." (PMID 36662765, 2023).
insulinoma (2 papers, 2022 to 2024). "The insulin pattern in patients with insulinomas might be affected by the presence of high calcium and PTH, as an additional standpoint of the strong interplay of PTH/calcium/insulin." (PMID 38928056, 2024). "In contrast, PHPT was diagnosed at an older age (35.79 ± 14.19 years) than insulinoma, and the mean age of patients with asymptomatic PTHT (95.4%, 41/43) that was detected only by laboratory testing of serum PTH and Ca was even older (36.15 ± 14.32 years)." (PMID 35698198, 2022).
Intellectual disability (2 papers, 2017 to 2025). "Additionally, there may be inconsistent resistance to various hormones, such as parathyroid hormone or thyrotropin, which is rare, and a frequent neurological involvement leading to mild to moderate intellectual disability." (PMID 41464128, 2025).
kidney cancer (2 papers, 2017 to 2025). Primary or metastatic malignant neoplasm involving the kidney. "This case describes an older patient with a history of increased PTH, several jaw lesions, and kidney cancer, all clinical manifestations of HPT-JT, which was diagnosed by genetic testing." (PMID 40115416, 2025). "Also, five parathyroid hormone-related proteins (PTHrPs) (PTHLH, PTH, HCRT, MC2R, and PTH2) are prominent for three kidney cancers (KICH, KIRC, and KIRP)." (PMID 28676692, 2017).
kidney transplant (2 papers, 2022 to 2024). A surgical procedure in which one or both kidneys from a donor are implanted into a recipient. "Among long-term kidney transplant recipients there are persistently high levels of FGF-23 and PTH." (PMID 35602513, 2022).
lactose intolerance (2 papers, 2012 to 2022). "Higher PTH serum levels were seen in patients with lactose intolerance compared with those without (42.03 ± 16.0 vs. 32.01 ± 17.6 pg/ml; p = 0.04)." (PMID 22584049, 2012).
Laryngomalacia (2 papers, 2018 to 2023). Laryngomalacia is a congenital abnormality of the laryngeal cartilage in which the cartilage is floppy and prolapses over the larynx during inspiration. "In the mild laryngomalacia group, the Ca, P, and PTH levels were high, and the lowest levels were seen in the severe group." (PMID 38813002, 2023). "The levels of Ca, P, and PTH were observed to decrease when examined according to laryngomalacia type." (PMID 38813002, 2023). "A statistically significant difference was determined between the moderate and severe laryngomalacia groups and the control group regarding PTH levels (p < 0.001)." (PMID 38813002, 2023). "A statistically significant difference was determined between the moderate and severe laryngomalacia groups and the control group with respect to PTH levels (p < 0.001)." (PMID 38813002, 2023). "A statistically significant difference was determined between the laryngomalacia group and the control group with respect to 25-OH-D and PTH levels (p < 0.001)." (PMID 38813002, 2023). "When examined according to laryngomalacia type, statistically significant differences were determined between the groups for 25-OH-D, Ca, P, PTH, and ALT values." (PMID 38813002, 2023). "When data were examined according to laryngomalacia types, a statistically significant difference was determined between the groups for 25-OH-D, Ca, P, PTH, and ALT values." (PMID 38813002, 2023). "A statistically significant difference was determined between the laryngomalacia patients and the control group with respect to 25-OH-D and PTH levels (p < 0.001)." (PMID 38813002, 2023). "When laryngomalacia was classified according to types in the current study, significant differences were determined between the groups for Ca, P, PTH, and ALT." (PMID 38813002, 2023). "Further research into low PTH levels among infants with laryngomalacia may provide an explanation of the changes in Ca metabolism." (PMID 38813002, 2023). "In addition, the reduction in PTH levels in infants with laryngomalacia may be explained by the change in Ca metabolism." (PMID 38813002, 2023). "In the current study, 25-OH-D, PTH, and BUN levels were observed to be lower in the laryngomalacia patient group than in the control group." (PMID 38813002, 2023).
leukopenia (2 papers, 2016 to 2023). "Uraemic retention solutes such as parathyroid hormone, polyamines, angiongenin and complement factor D may all impair neutrophil activity by causing inappropriate expression of cell adhesion molecules that result in a transient leukopenia." (PMID 27090094, 2016).
malabsorption syndrome (2 papers, 2016 to 2022). A syndrome resulting from the inadequate absorption of nutrients in the small intestine. "Secondary causes of an elevated PTH—such as renal compromise (creatinine clearance of less than 60 mL/min), 25-hydroxyvitamin D insufficiency (less than 30 ng/mL or 80 nmol/L), primary hypercalciuria, malabsorption syndromes, and medications such as lithium or thiazides—must be excluded." (PMID 27508075, 2016).
mastitis (2 papers, 2024 to 2025). Inflammation of breast tissue during lactation or postpartum due to an obstructed duct or infection. "However, persistent inflammation—such as that originating from mastitis or metritis—can suppress PTH responsiveness and alter vitamin D metabolism." (PMID 40284849, 2025). "For example, a herd experiencing subclinical mastitis may show only borderline-low calcium levels, yet the accompanying inflammatory environment could suppress PTH release and disrupt vitamin D metabolism." (PMID 40284849, 2025).
melanoma (2 papers, 2020 to 2024). A malignant, usually aggressive tumor composed of atypical, neoplastic melanocytes. "As observed for PTH‐differentiated osteoblast cells, incubation of hFOB 1.19 precursors with melanoma‐CM was sufficient to increase expression of the osteoblast markers PTHrP and SPP1." (PMID 31323160, 2020).
memory impairment (2 papers, 2023 to 2024). "Vitamin D was significantly lower in patients who gave a positive answer to the NMSQ questions about memory impairment (p = 0.036), while PTH levels were higher in patients with constipation (p = 0.044), trouble in having sex (p = 0.021), and leg restlessness (p = 0.020)." (PMID 36873448, 2023).
metastatic prostate carcinoma (2 papers, 2001 to 2009). A carcinoma that arises from the prostate gland and has spread to other anatomic sites. "In theory, osteoblastic lesion in skeletal sites of metastatic prostate cancer causes hypocalcemia that in turn leads to calcium-sensing receptor (CaSR) activation, resulting in increased PTH production and secretion." (PMID 19602280, 2009). "Increased serum level of parathyroid hormone (PTH) was found in metastatic prostate cancers." (PMID 19602280, 2009).
Osteolysis (2 papers, 2015 to 2022). Osteolysis refers to the destruction of bone through bone resorption with removal or loss of calcium. "First, a suprapharmacological dose was selected and the results provided little insight into whether therapeutic levels of intermittent PTH could be used to treat particle-induced osteolysis." (PMID 26441073, 2015).
paraganglioma (2 papers, 2016 to 2022). A benign or malignant neoplasm arising from paraganglia located along the sympathetic or parasympathetic nerves. "Paragangliomas will show positivity for synaptophysin, chromogramin, and S100 protein stains in sustenticular cells with negativity for PTH." (PMID 28003924, 2016).
Pediatric Cancer (2 papers, 2024). "This retrospective study examines associations between PTH, 25-OH vitamin D (25OHD), and event-free survival (EFS) and overall survival (OS) in patients with pediatric cancer." (PMID 39141058, 2024). "In summary, this study highlights the potential role of elevated PTH as a prognostic marker for poor outcomes in patients with pediatric cancer." (PMID 39141058, 2024). "Higher LPA and MVPA levels were related to higher PTH levels in young survivors of pediatric cancer." (PMID 39599700, 2024).
primary failure of tooth eruption (2 papers, 2013 to 2023). "The cause is generally attributed to resorption of the permanent periodontal membrane due to malfunction in the peripheral nerve tissue (genetically determined or caused by virus attacks) or primary failure of tooth eruption (PFE) (defect in the receptor for parathyroid hormone, PTH1R)." (PMID 36980140, 2023).
prostate tumor (2 papers, 2014 to 2016). "There is evidence from in vivo models that expanding the Ob niche with the use of parathyroid hormone, increased the number of DTCs in bone from sub-cutaneous prostate tumours." (PMID 27761376, 2016).
pulmonary embolism (2 papers, 2023). The obstruction of the pulmonary artery or one of its branches by an embolus, sometimes associated with infarction of the lung. "Pulmonary embolism (according to isolated reports) might be related to chronic hypercalcemia rather than an elevated PTH level underling a high calcium-induced pro-inflammatory and hyper-coagulation status, mechanisms that are yet to be determined." (PMID 37296804, 2023).